STAT3 (signal transducer and activator of transcription 3)
Diseases named in the same sentence as STAT3 in open-access papers (continued):
Sharing a sentence is not in itself a finding about the gene and the disease.
tumor (continued). "The blockade of the constitutive expression of STAT3 in tumor reduced the expression of VEGF, IL-6, and IL-10, which neutralized the inhibitory effect of dendritic cell maturation." (PMID 35936759, 2022). "Inhibiting TY2 blocks the activation of STAT3 by IL-10 and other pathways via T2, suppressing tumor cell survival via a bypass mechanism." (PMID 35211406, 2022). "In the hepatocellular carcinoma, toosendanin functions as WW-domain containing oxidoreductase (WWOX) agonist and thereby inhibits tumor metastasis by the inhibition of JAK2/Stat3 and Wnt/β-catenin signaling pathways." (PMID 36408249, 2022). "In that study, the addition of a Smo agonist also induced STAT3 activation, while removal of STAT3 from the mouse epidermis or disruption of IL‐11Ra/STAT3 signaling significantly reduced SmoM2‐driven tumor development." (PMID 34482626, 2022). "Mechanistically, OCLN knockdown inhibited IL8 expression and then reduced p‐STAT3 levels to interrupt tumour angiogenesis." (PMID 35224833, 2022). "Together, these data reveal a role for neutrophil-derived IL-1β in promoting iCAF polarization and inducing CAF-tumor cell IL-6/STAT3 signaling in the PDAC TME, which is a central mediator of chemoresistance." (PMID 36107485, 2022). "The adequate balance between STAT1 and STAT3 expression is very crucial for driving the macrophage polarization and tumor progression." (PMID 34689394, 2022). "The hyperactivation of STAT3 in anti-tumor immune cells exerts a negative regulatory effect that also contributes to an immunosuppressive tumor microenvironment." (PMID 36010899, 2022). "HGF/c-MET also interacts with the Src/STAT3/FAK/ERK signaling pathway to induce resistance to platinum-based drugs in tumor cells." (PMID 35684449, 2022). "STAT3 has been reported to be constitutively activated in both tumor and immune cells in the tumor microenvironment." (PMID 35158807, 2022). "The CXCL12/CXCR4 axis can also induce vascular endothelial growth factor (VEGF) expression through the JAK2/STAT3 pathway, inducing tumor angiogenesis." (PMID 35893797, 2022). "The suppression of STAT3 activation resulted in the downregulation of its targeted gene products, which are involved in tumor survival, angiogenesis and metastasis, and thereafter led to apoptosis and impaired cellular migration." (PMID 35956786, 2022). "Elevated levels of STAT3 phosphorylation were correlated with tumor invasion, metastasis, and the stage." (PMID 35056682, 2022). "The results showed that the H9C2 cell proliferation was more than that of the control group (si-NC), showing that the STAT3 gene was a tumor suppressor gene." (PMID 35645616, 2022). "This antibody affected both bulk tumor cells and tumor initiating cells, decreasing the capacity of self-renewal and tumor initiation through STAT3 signalling inhibition and the downregulation of the stemness gene Nanog." (PMID 35785191, 2022). "Radiofrequency ablation (RFA) of intrahepatic tumors induces distant tumor growth through activation of interleukin 6/signal transducer and activator of transcription 3 (STAT3)/hepatocyte growth factor (HGF)/tyrosine-protein kinase Met (c-MET) pathway." (PMID 35857766, 2022). "AKR1C1 interacts with STAT3 and promotes its phosphorylation, so as to promote the expression of downstream-related genes and finally promote tumor metastasis." (PMID 35370661, 2022). "In CRC, ILC3s produced IL-22 which activated STAT3 phosphorylation signaling to promote the development and invasion of tumor." (PMID 36246629, 2022). "In the untreated cells, Stat3 (red punctate) staining was predominantly localized in the nucleus of the tumor cells, with weak presence in the cytoplasm (Stat3, red merged with blue DAPI nuclear staining)." (PMID 35276290, 2022). "Research findings demonstrated that glycyrrhizic acid, a bioactive compound in licorice, induces apoptosis in TF-1 leukemia cells via blocking Akt, mTOR, and STAT3 phosphorylation signaling in tumor tissues." (PMID 36428613, 2022).
tumor (continued). "In the majority of cases, inhibition of STAT3 signaling switches the tumor microenvironment towards immune activation (right)." (PMID 35865518, 2022). "The STAT3 signal transduction pathway is critical in the interaction of tumor cells with the microenvironment." (PMID 35203636, 2022). "The process of immunosuppression is reflected in that these cytokines can activate IL-6R+ malignant cells and myeloid cells, thereby activating STAT3 signaling and promoting tumor growth." (PMID 35965504, 2022). "Elevated levels of CAF-derived IL-6 induces the activation of the JAK/STAT3 signaling pathway, leading to tumor cell proliferation mediated by the activation of cyclin D1, among other cell cycle mediators." (PMID 36010899, 2022). "The KD of MVP stimulated STAT3 (signal transducer and activator of transcription 3) and accelerated tumor growth." (PMID 35681764, 2022). "Alternative splicing generates STAT3α and STAT3β; STAT3α is the full-length form of STAT3 and acts as a tumor promoter, while STAT3β lacks a transcriptional activation domain." (PMID 35810312, 2022). "A recent study has proposed the manipulation of MMP generation via activating signal transducer and activator of transcription 3 (STAT3) to catalyze the matrix degeneration and cellular disconnection, thus facilitating the metastasis of tumor cells." (PMID 36091126, 2022). "Next, we ascertained if neutrophil-derived IL-1β was contributory to CAF-tumor cell IL-6/STAT-3 signaling." (PMID 36107485, 2022). "Expression of activated MEK1, activated AKT, activated mTOR or activated STAT3 all also reduced tumor cell killing by the drug combination, with expression of activated STAT3 trending towards being the most protective." (PMID 35136485, 2022). "Previous data indicated, STAT3 Signaling activation in tumor-initiating cells (CSCs) in claudin-low models of human BC87." (PMID 36418345, 2022). "The increased activation of STAT3 in cancer cells results in the expression of various oncogenes that induce tumor metastasis, stemness, proliferation, angiogenesis, and anti-apoptosis." (PMID 35927628, 2022). "Tumour resistance is increased through signal transducer and activator of transcription 3 (STAT3), apoptosis inhibiting proteins from the BCL2 family and by loss of expression of tumour antigen." (PMID 35445563, 2022). "STAT3 is a molecule found downstream of many signal cascades and is known to be active in many neoplasms." (PMID 36499710, 2022). "Ultimately, these results highlight how STAT3 antagonism can alter the immunosuppressive tumor microenvironment and subsequently improve the antitumor immune response." (PMID 36011015, 2022). "In the present study, we provided new insight into LCN2 as a potential biomarker for the prediction of CAC, and demonstrated that LCN2 is a key regulator of cell survival and tumor development mediated by STAT3/NF-kB activation." (PMID 35470375, 2022). "IL-6/STAT3 axis-mediated Glut5 expression enhances fructose uptake and utilization, and promotes tumor cell growth." (PMID 35813468, 2022). "In line with our NF-κB findings, IHC revealed a largely decreased expression of phosphorylated STAT3 (p-STAT3) in the tumor lesions of anti–IL-1β–treated mice at the age of 14 or 18 weeks." (PMID 35471938, 2022). "One study demonstrated that the STAT3 inhibitor WP1066 induced immunostimulatory cytokine release to promote T-cell effector function in murine models while also decreasing tumor-mediated immunosuppressive mechanisms of Treg and M2 macrophage accumulation." (PMID 36011015, 2022). "Anti-IL-6R antibody therapy suppressed STAT3 activation and attenuated tumor burden in Apcmin/+Ripk3-/- mice." (PMID 33996591, 2021). "Supporting the finding that JAK2/STAT3 suppresses STING in tumor cells, co-administration of IL-6, a JAK2/STAT3 activator, impaired the anti-tumor effects of cGAMP." (PMID 33790360, 2021).
tumor (continued). "IL22RA1 is a receptor of interleukin 22, has been reported working as a signal transducer and activator of STAT3 signaling in the malignant transformation, it plays an important role in promoting tumor growth and metastasis and inhibiting cell apoptosis." (PMID 34040139, 2021). "We and others have also reported that genetically altering STAT3 at K685 inhibits tumor progression, suggesting that acetylated STAT3 is a valid target to develop anticancer therapeutics." (PMID 33491667, 2021). "An intrinsic immune-surveillance system can be activated by the suppression of STAT3 activity in hematopoietic cells, thus inhibiting tumor growth and metastasis." (PMID 33435880, 2021). "Enhanced levels of IL-6 play a key role in STAT3 signaling in tumor formation and the development of CRC." (PMID 33996591, 2021). "Decreased cell proliferation and angiogenesis were shown in PS-acet.-STAT3 peptide–treated tumor tissues." (PMID 33491667, 2021). "Of note, mesenchymal stem cells in the tumor microenvironment can also be induced to differentiate into CAFs through activation of the JAK/STAT3 signaling cascade." (PMID 34944848, 2021). "Actually, phosphorylated STAT1 and STAT3 dimer in tumor cytosol can bind to the PD-L1 promoter to induce PD-L1 expression while inhibition of STAT3 activity by STATTIC mitigates the CXCR3 activation-induced PD-L1 expression in tumor cells." (PMID 33407095, 2021). "RAGE-mediated tumor responses are triggered by the STAT3 and NF-kB transcription factors, which, in turn, enhance tumor metastasis." (PMID 33466626, 2021). "PEG-PLL-PLLeu micelles co-delivering STAT3 siRNA and ovalbumin elevated expression levels of CD86 and CD40 as well as IL-12 produced by tumor-associated DCs." (PMID 33668746, 2021). "Compared to the vehicle and IFN-α groups, tumor tissues of the CIB-6 group showed decreased levels of p-STAT3 and β-catenin, and the expression level of β-TrCP was increased, thereby aligning with the results observed in vitro." (PMID 33805945, 2021). "IL-17A enhanced tumor growth in vivo via induction of IL-6, activating oncogenic transcription factor STAT3 and stimulating pro-survival and pro-angiogenic tumor genes." (PMID 35008550, 2021). "Constitutive STAT3 activation plays an important role in driving tumorigenesis and tumor cell death resistance, and the inhibition of STAT3 activation in a tumor is involved in mitochondrial depolarization and mitochondrial-associated apoptotic pathways." (PMID 34277607, 2021). "The Western blotting results indicated that the expression of STAT3 and p-STAT3 (Ser727) was decreased in MDSCs that were isolated from tumor sites after ZQT gavage." (PMID 33867859, 2021). "STAT3 is constitutively activated in tumor-infiltrating immune cells, and genetic ablation of STAT3 in these cells unleashes an intrinsic immune-surveillance system that abrogates tumor growth and metastasis in mice." (PMID 34944848, 2021). "We found a strong increase in the STAT3 phosphorylation signal in the secondary resistant tumor in three of the four SR PDX tumors generated." (PMID 34271981, 2021). "To determine if MAFF and its downstream targets, IL11/STAT3, play a significant role in tumor metastasis, we performed in vivo experiments using MDA-MB-231 cells injected into the mammary fat pad of NSG mice." (PMID 34262028, 2021). "To understand the underlying molecular mechanism of Tris DBA-induced cytotoxicity, we evaluated the potential of Tris DBA to modify STAT3 phosphorylation in tumor cells and noticed a marked decline in the activation of STAT3 in all the tested cell lines." (PMID 34771643, 2021). "Previous studies have reported that the EGFR and Src-mediated STAT3 signalling pathways can contribute to tumour aggressiveness and treatment resistance." (PMID 34407787, 2021). "STAT3 ablation in tumour cells leads to improved immune function of DCs, NK cells, T cells and neutrophils, and tumour regression in vivo." (PMID 33382511, 2021).
tumor (continued). "Research indicates that STAT3 is a potential therapeutic target for OS therapy successfully inhibiting the proliferation, migration, progression and invasion of tumour cells." (PMID 33382511, 2021). "We next investigated to what extent PS-acet.-STAT3 peptide diminishes STAT3 activity in tumor cells in vitro." (PMID 33491667, 2021). "An association of Arid5a-regulated molecules, such as IL6, Tbet, Stat3, Ox40, and Pparγ, has been widely studied in various cancers and tumor models." (PMID 35126382, 2021). "Silencing STAT3 and PD-L1 antibody injection in combination increased apoptosis in tumor cells and thus offers better anti-cancer activity." (PMID 34881181, 2021). "Constitutive STAT3 activity appears to inhibit the anti‐tumour response by immune cells, including dendritic cells (DCs), T cells, natural killer (NK) cells and neutrophils." (PMID 33382511, 2021). "For instance, BC cell line models have been shown to carry activating mutations in Src kinases, which also modulate STAT3 and its effect on proliferation, and anti-STAT3 strategies has been shown to reduce tumour growth in animal studies." (PMID 34834425, 2021). "These cytokines can mediate the activity of transcription factors NF-κB and STAT3, which has important roles in dysplastic lesion, neoplasia, angiogenesis and extracellular matrix synthesis during CRC progression." (PMID 33536421, 2021). "AKT-stimulated pS21 EZH2 was capable of accelerating EZH2-STAT3 intercommunication and augmenting EZH2-mediated methylation as well as activities of STAT3 resulting in the facilitation of GSC self-renewal as well as GBM tumor progression." (PMID 34745848, 2021). "In this review we will focus on the pro-tumorigenic effects of CAFs and how the transcription factor STAT3 modulates the tumor-promoting activities of CAFs in the TME." (PMID 34858425, 2021). "Consistent with our in vitro findings, additional biochemical analyses of MDA-MB-231 and MDA-MB-231-DTR tumor tissues from vehicle-treated groups revealed that activated STAT3 (p-STAT3 (Y705)) is considerably upregulated in resistant tumor tissues." (PMID 33920736, 2021). "Recent works have highlighted the importance of signaling pathways downstream of STAT3 that are responsible for MDSC differentiation in tumor models." (PMID 33579907, 2021). "The cellular retention of PS-acet.-STAT3 peptide in tumors in vivo was assessed by fluorescent IHC staining of tumor tissue sections followed by confocal imaging." (PMID 33491667, 2021). "STAT3 is often hyperactivated in tumor-infiltrating immune cells and negatively regulates natural killer (NK) cells, neutrophils, effector T cells, and dendritic cells (DCs)." (PMID 35155571, 2021). "STAT3 is one of the widely-studied transcription factors that encourage tumor initiation and progression, antiapoptosis, and metastasis." (PMID 35053027, 2021). "The persistent activation of STAT3 mediates tumor-promoting inflammatory pathways, including nuclear factor-κB (NF-κB) and interleukin-6 (IL-6)–GP130–Janus kinase (JAK) pathways." (PMID 33509150, 2021). "STAT3 is a transcription factor that plays a key role in the production of immunosuppressive factors and promotion of cancer cell proliferation in the tumor microenvironment." (PMID 34869005, 2021). "We here summarize current knowledge on how gp130 signalling and STAT3 in tumour cells and cells of the tumour micro-environment drives hepatic tumorigenesis." (PMID 34047814, 2021). "STAT3 regulates a variety of important genes involved in aggressive tumor behavior, stem cell properties, and cancer chemoresistance." (PMID 34572725, 2021). "Recent reports investigated the pro-survival mechanisms of TYK2 signaling using pharmacologic or genetic inhibition of TYK2 or STAT3 in various cancer cell lines and mouse tumor models." (PMID 34439323, 2021). "Results showed that IL-6/JAK/STAT3 signaling, complement and mitotic spindle were three pathways that mostly enriched in tumor samples." (PMID 34544443, 2021).
tumor (continued). "Several studies have highlighted the role of tumor-cell intrinsic STAT3 signaling in modulating the tumor microenvironment of NSCLC." (PMID 34944848, 2021). "Signal transducer and activator of transcription 3 (STAT3) is a transcription factor activated by cytokines and growth factors involved in inflammation, tumor cell proliferation and invasion." (PMID 34425750, 2021). "Another study in cholangiocarcinoma showed that tumor cell-derived extracellular vesicles can “educate” MSCs to induce local microenvironmental changes that facilitate tumour cell growth via IL-6/STAT-3 signaling pathway." (PMID 34513701, 2021). "As the HCCLM3 cell line expresses substantial levels of constitutively active STAT3, the potential of 3FC to inhibit the deregulated STAT3 phosphorylation in these tumor cells was first examined." (PMID 35053027, 2021). "Based on these data, our work suggests a safe therapy by combining using p-STAT3 inhibitor Stattic and anti-PD-1 to regulate tumor immune therapy." (PMID 33936081, 2021). "Immunoprecipitation and Western blotting of tumor tissues showed that treatments with PS-acet.-STAT3 peptide downregulated STAT3 activation in HCT116 tumor xenografts." (PMID 33491667, 2021). "Since PRMT5 depletion reduced expression of STAT3 target genes, we analyzed the status of STAT3 tyrosine phosphorylation at Y705 (p‐STAT3) in mouse tumor samples." (PMID 34026434, 2021). "Activated STAT3 usually forms a dimer, then rapidly translocate from cytoplasm into the nucleus, triggering the transcription of the downstream genes involved in tumor proliferation and survival." (PMID 34922636, 2021). "Crosstalk between CAFs and tumor cells is essential for tumor progression which is in part dictated by intrinsic STAT3 activity in CAFs." (PMID 34858425, 2021). "To understand how the STAT3 pathway regulates the tumor infiltrated Treg cells, we evaluated the expression of Tim-3 and immunosuppressive cytokines." (PMID 33936081, 2021). "Its induction in endothelial cells has been shown to suppress tumor angiogenesis via reduction of mTOR-mediated phosphorylation and activation of STAT3 and resulting VEGFa expression." (PMID 34128833, 2021). "The first signal controls IMCs production, mainly mediated by tumor-derived growth factors, such as IL-6, IL-11, IL-17A, G-CSF, GM-CSF, TNFα, and involves signal pathways including STAT3, IRF8, C/EBPβ, RB1, Notch, adenosine receptors A2b, NLRP3, and others." (PMID 34680276, 2021). "IL-6 is a pro-inflammatory cytokine frequently detected in the tumor microenvironment to induce inflammation and activate STAT3 signaling in cancer cells." (PMID 34887764, 2021). "Collectively, these findings demonstrate an inhibitory effect of STAT3 signaling on anti-tumor NK immunity in carcinogen-induced tumors." (PMID 34944848, 2021). "MIF is a pleiotropic cytokine that regulates inflammation, cell proliferation, and differentiation, and also promotes tumor cell proliferation, angiogenesis, and metastasis by activating the STAT3, ERK, and PI3K/AKT signaling pathways." (PMID 33431808, 2021). "STAT3 activates target genes that are thought to promote tumor progression, including cell proliferation, migration, and invasion." (PMID 34503167, 2021). "We prospect that targeting CREPT can be used to develop synthetic inhibitors for STAT3-related tumours." (PMID 33531691, 2021). "Atsaves STAT3 is a transcription factor that plays a key role in the production of immunosuppressive factors and promotion of cancer cell proliferation in the tumor microenvironment." (PMID 34869005, 2021). "This approach has been used successfully to target STAT3 activation in NSCLC by enhancing tumor cell apoptosis." (PMID 34944848, 2021). "Results showed a lead analogue selectively inhibited IL6-dependent activation of JAK2 and STAT3 and suppressed tumour progression both in vitro and in vivo in xenograft lung cancer models." (PMID 34834425, 2021).